SMARCD3 (SWI/SNF related BAF chromatin remodeling complex subunit D3)
Diseases named in the same sentence as SMARCD3 in open-access papers (continued):
Sharing a sentence is not in itself a finding about the gene and the disease.
SMARCD3 also shares sentences with these, for which no sentence is quoted: Insulin resistance (3 papers); atherosclerosis (2); diabetes (2); dilated cardiomyopathy (2); abdominal aortic aneurysm (1); acute myeloid leukemia (1); astroblastoma (1); breast tumor (1); cardiac diseases (1); cardiac hypertrophy (1); cardiomyopathy (1); cardiovascular diseases (1); COVID-19 (1); Duchenne muscular dystrophy (1); gastric adenocarcinoma (1); glioma (1); heart defects (1); heart failure (1); hepatocellular carcinoma (1); Hypertension (1); infectious disease (1); influenza (1); Intellectual disability (1); myocardial infarction (1); neuroblastoma (1); Obesity (1); osteoarthritis (1); ovarian serous cystadenocarcinoma (1); Pan (1); renal cell carcinoma (1).
A further 4 diseases each share a sentence with SMARCD3 in 1 paper.